CHI3L1 (chitinase 3 like 1)
Diseases named in the same sentence as CHI3L1 in open-access papers (continued):
Sharing a sentence is not in itself a finding about the gene and the disease.
colitis (21 papers, 2015 to 2025). Inflammation of the colon. "In both this animal model and human patients with IBD-associated dysplasia or cancer, fecal CHI3L1 levels increase in parallel with inflammatory progression and positively correlate with the onset of colitis-associated cancer." (PMID 40643503, 2025). "In particular, CHI3L1 is likely to be a reliable biomarker for colitis-associated epithelial neoplastic changes during monitoring IBD patients in the remission phase." (PMID 33573291, 2021). "Notably, CHI3L1 plays a significant role in colitis-associated cancer, as suggested by findings from animal models of IBD." (PMID 40643503, 2025). "Moreover, a deficiency of Chi3l1 leads to an imbalance in the gut microbiota, which exacerbates colitis induced by dextran sodium sulfate." (PMID 39373714, 2024). "ELISA quantification showed a step-wise increase in CHI3L1 levels in both serum and stool of the untreated WT mice to WT mice that had undergone 1 cycle of DSS and to AOM/DSS treated WT mice, indicating that CHI3L1 levels are positively associated with the progression of colitis and CAC." (PMID 26431492, 2015). "In the WT mice, colonic IHC staining revealed a high Ki-67 labeling index during the onset of acute DSS-induced colitis, which further expanded as it progressed into the chronic phase, showing a strong association with the step-wise increase of CHI3L1 expression during the distinct disease phases." (PMID 26431492, 2015). "Our early experimental studies demonstrated that CHI3L1 expression was significantly upregulated in the colonic tissues of DSS-induced colitis." (PMID 41008172, 2025). "This study identifies a therapeutic target for colitis patients and provides a theoretical foundation for SPS-targeted CHI3L1 therapy in colitis treatment." (PMID 41008172, 2025). "In our study, CHI3L1 expression was significantly elevated in colitis rats as well as in epithelial cells and macrophages, which aligns with prior findings." (PMID 41008172, 2025). "As noted in the previous section, a study using the AOM/DSS model revealed that CHI3L1 KO mice developed more severe colitis than WT mice but exhibited a significantly lower tumor incidence." (PMID 40643503, 2025). "The mRNA expression levels of Cxcr2, Chi3l1 and S100a9 in colitis mice were significantly higher than those in control group, especially S100a9, which was consistent with our bioinformatics analysis results." (PMID 38448514, 2024). "S100A9 is highly expressed during the acute phase of colitis; however, it is down-regulated by colonic chitinase-3-like 1 (CHI3L1), a pseudo-chitinase that is upregulated during the chronic phase of colitis." (PMID 34572138, 2021). "Like CHI3L1, the damage-associated molecular (DAMP) protein S100A9 is also usually undetectable in healthy colons, but can be induced in colonic mucosa during colitis." (PMID 26431492, 2015). "Here we demonstrate that CHI3L1 (aka Brp39) knockout (KO) mice treated with azoxymethane (AOM)/dextran sulphate sodium (DSS) developed severe colitis but lesser incidence of CAC as compared to that in wild-type (WT) mice." (PMID 26431492, 2015). "In this current study, the induction phase of acute colitis renders a lower level of CHI3L1 expression compared to the later chronic phase of colitis." (PMID 26431492, 2015). "CHI3L1 expression levels appear to be highest during the recovery phase from acute colitis, which reflects one of its major functions in tissue restitution by promoting cell survival and proliferation." (PMID 26431492, 2015). "In vivo, neutralizing CHI3L1 with an antibody suppresses DSS-induced colitis, and this neutralization dramatically decreases bacteria adhesion and invasion of epithelial cells." (PMID 26085826, 2015). "Here, we show that CHI3L1 expression is required for IECs survival by promoting the proliferation of these cells during the transitional phases of colitis and CAC, in part through the competitive inhibition of S100A9 binding to the RAGE." (PMID 26431492, 2015).
colitis (continued). "Additionally, previous research results demonstrated that CHI3L1 was specifically upregulated in the colonic epithelial cells and lamina propria macrophages of experimental murine colitis." (PMID 41008172, 2025). "In summary, we hypothesize that in colitis, intestinal epithelial cells secrete CHI3L1, which subsequently mediates M1 macrophage polarization, thereby exacerbating colitis pathological progression." (PMID 41008172, 2025). "The interaction is mediated by the CBD of the AIEC chitinase ChiA that recognizes CHI3L1, and, more specifically, the N-glycosylation of asparagine 68 residue in mouse CHI3L1, this specific interaction promoting pathogenic effects of AIEC in mice with colitis." (PMID 32466328, 2020). "Interestingly, an acute colitis can be exacerbated via CHI3L1 overexpression favoring bacterial adhesion and internalization into IECs." (PMID 32466328, 2020). "Building on this evidence, the current study hypothesized that epithelial-immune cell crosstalk may exist in colitis, where inflammatory-injured epithelial cells promote macrophage polarization toward pro-inflammatory M1 phenotype through excessive CHI3L1 secretion." (PMID 41008172, 2025). "In summary, this study shows a 'scaffold model' for microbiota homeostasis by interaction between intestinal Chi3l1 and bacteria cell wall interaction, and it also highlights that an unbalanced gut microbiota in the intestinal mucus contributes to the development of colitis." (PMID 39373714, 2024). "Consequently, inhibition of chitinases AMCase and CHIT1, and also of the chitinase-like protein YKL-40 (CHI3L1), may prove a viable strategy for treatment of inflammatory and fibrotic diseases, including colitis." (PMID 35216274, 2022). "In the colitis-associated cancer mouse model, colonic chitinase 3-like 1 (CHI3 L1) can bind to RAGE, and thus disrupt the S100A9-associated expression positive feedback loop during early immune activation, creating a S100A9 low colonic environment, especially in the later phase of colitis." (PMID 29942307, 2018). "This CHI3L1-mediated cell proliferation/survival involves partial downregulation of the pro-apoptotic S100A9 protein that is highly expressed during the acute phase of colitis, by binding to the S100A9 receptor, RAGE (Receptor for Advanced Glycation End products)." (PMID 26431492, 2015). "However in Brp39 KO mice, Ki-67 positive cells dramatically decreased during the acute phase of colitis and almost undetectable during the chronic phase, indicating the CHI3L1 expression is crucial for the proliferation of IECs during the course of intestinal inflammation." (PMID 26431492, 2015). "The observation that Fh15 treatment significantly reduced the levels of CHI3L1 and S100A9 is, therefore, consistent with the substantial reduction in the number of neutrophils and macrophages in the colonic tissue of colitis mice." (PMID 40497975, 2025). "Building upon previous findings from our research group demonstrating elevated CHI3L1 expression in DSS-induced colitis models, we conducted tracking experiments in TNBS-induced colitis rats." (PMID 41008172, 2025). "In conclusion, CHI3L1 serves as a key molecule linking epithelial inflammation to macrophage polarization, and its mechanism of regulating the immune microenvironment through the STAT3/NF-κB pathway provides a novel therapeutic target for colitis." (PMID 41008172, 2025). "CHI3L1 is critical in the activation of the AKT pathway, and AKT activation may be important in colitis development." (PMID 36615523, 2022). "This review addresses selected laboratory biomarkers (including ANCA, chitinase 3-like 1, S100A12/RAGE, calprotectin, and TNF/TNFR2), which are identified by utilizing two well-accepted animal models of colitis, dextran sodium sulfate-induced and T cell receptor alpha knockout colitis models." (PMID 33573291, 2021).
colitis (continued). "In addition, our in vivo and in vitro results demonstrated that expression of CHI3L1 and S100A9 are inversely correlated in acute- and chronic-DSS-induced colitis in WT and Brp39 KO mice." (PMID 26431492, 2015). "Highest CHI3L1 expression was found during the chronic phase of colitis, rather than the acute phase, and is essential to promote intestinal epithelial cell (IEC) proliferation in vivo." (PMID 26431492, 2015). "AOM/DSS treatment in the Brp39 KO BM -> WT BMT-chimeric mice resulted in a BW profile that is intermediate between WT and Brp39 KO mice, suggesting that the CHI3L1 expression in the non-hematopoietic cells, presumably IECs, can partially ameliorate colitis." (PMID 26431492, 2015). "Conversely, in the Brp39 KO mice, Annexin V levels were increased during the transitional phases in the course of colitis, presumably a result of imbalance between high S100A9 and no CHI3L1 expression levels." (PMID 26431492, 2015).
frontotemporal dementia (20 papers, 2010 to 2025). Frontotemporal dementia (FTD) comprises a group of neurodegenerative disorders, characterized by progressive changes in behavior, executive dysfunction and language impairment, as a result of degeneration of the medial prefrontal and frontoinsular cortices. "The ISH signal showed robust CHI3L1 transcription in SIVE and MS, focal ISH signal in chronic infarct cases while AD, ALS, Pick's disease and schizophrenia showed a few scattered positive cells in some areas while other areas were negative." (PMID 20540736, 2010).
amyotrophic lateral sclerosis (19 papers, 2015 to 2025). Amyotrophic lateral sclerosis (ALS) is a neurodegenerative disease characterized by progressive muscular paralysis reflecting degeneration of motor neurons in the primary motor cortex, corticospinal tracts, brainstem and spinal cord. "In addition, CHI3L1 has been associated with various other neurological diseases, i.e., Parkinson’s disease (PD), amyotrophic lateral sclerosis, Huntington’s disease, MS, progressive supranuclear palsy, and epilepsy." (PMID 38177294, 2024). "In amyotrophic lateral sclerosis, CHI3L1 has been shown to promote astrocyte activation and motor neuron death." (PMID 38177294, 2024). "It is possible that expression of CHI3L1 with advancing neurodegeneration is deleterious, as shown for instance by its inverse correlation with survival in amyotrophic lateral sclerosis." (PMID 33584248, 2020). "In accordance with this idea, elevated levels of CHI3L1 have been observed in a variety of neurological disorders, such as traumatic brain injury, ischemic stroke, Alzheimer’s disease, Parkinson’s disease, amyotrophic lateral sclerosis (ALS), and glioma." (PMID 39768177, 2024).
metabolic syndrome (19 papers, 2012 to 2025). A cluster of metabolic risk factors for CARDIOVASCULAR DISEASES and TYPE 2 DIABETES MELLITUS. "In T2DM patients, Chi3l1 is also correlated with metabolic syndrome, dyslipidemia, and glycemic parameters such as HbA1c, albuminuria, and fasting glucose." (PMID 39769202, 2024). "Positive associations between SNPs of CHI3L1 and lipid levels were found, but could not be replicated in a similar but larger population, and therefore we cannot make any conclusions about the possible role of YKL-40 in the development of dyslipidemia." (PMID 23071724, 2012). "In women with HIV and central obesity, the adipocytokine adiponectin and Chi3L1, a marker of liver steatosis and metabolic syndrome, decreased significantly following switch to RAL, but not with continued PI or NNRTI." (PMID 29746485, 2018). "Exploratory associations with CRP and lipids showed that CHI3L1 expression did not correlate with CRP or lipid markers in healthy controls or MCI (all p > 0.05), arguing against baseline systemic inflammation or dyslipidemia as primary drivers of group differences." (PMID 41425914, 2025).
Arthritis (18 papers, 2009 to 2025). Inflammation of a joint. "The serum as well as tissue levels of CHI3L1 are significantly elevated in patients with IBD including UC and CD, and the elevation of serum CHI3L1 is primarily associated with the severity, the extent of inflammation, and the existence of complications such as arthritis." (PMID 38667293, 2024). "In turn, CHI3L1 was detected in RA synovial fluid and tissue from patients with arthritis, and the synovial fluid of three out of 10 patients with spondylarthritis exhibited endogenous CHI3L1 expression." (PMID 38177294, 2024).
osteosarcoma (18 papers, 2011 to 2025). A usually aggressive malignant bone-forming mesenchymal neoplasm, predominantly affecting adolescents and young adults. "First discovered in human osteosarcoma cells, Chitinase-3-like 1 (CHI3L1), also called YKL-40, is the most widely known and studied chitinase-like protein." (PMID 38791588, 2024). "CircMMP9 is present in advanced osteosarcoma, it sponges miR-1265 activating chitinase-3-like protein 1 (CHI3L1) circMMP." (PMID 37232745, 2023). "CHI3L1 can be expressed by a variety of cells, including chondrocytes, smooth muscle cells, and osteosarcoma cells, but its function is usually related to inflammation and tissue remodeling." (PMID 35190738, 2022). "Chitinase-3-like 1 protein (YKL-40) is a secreted glycoprotein originally isolated from human osteosarcoma cells." (PMID 33685523, 2021). "Chitinase 3‐like protein 1 (CHI3L1) (also known as YKL‐40) was discovered in human osteosarcoma cell line MG63 by Johansen et al10 in 1992." (PMID 31536166, 2020). "CHI3L1 is a secreted glycoprotein originally isolated from human osteosarcoma cells." (PMID 38110934, 2023). "Moreover, following its initial identification in the culture supernatant of the MG63 osteosarcoma cell line, CHI3L1 has been shown to be overexpressed in a wealth of both human cancers and animal tumor models." (PMID 32929074, 2020). "YKL-40, also known as human cartilage glycoprotein-39 or chitinase-3-like-1, is a secreted glycoprotein originally identified from culture medium of a human osteosarcoma cell line MG-63." (PMID 21991364, 2011). "It has been reported that circ-CHI3L1.2 knockdown promotes apoptosis and attenuates resistance of CDDP-resistant osteosarcoma cells." (PMID 35070998, 2021). "Additionally, the knockdown of circ-CHI3L1.2 downregulates the expression levels of P-gp, MRP1, and GSTP1 and weakens CDDP resistance in osteosarcoma." (PMID 35070998, 2021).
prostate carcinoma (18 papers, 2014 to 2025). A carcinoma that arises from epithelial cells of the prostate gland. "Adjusted odds ratios (AORs) and 95% confidence intervals (CIs) of prostate cancer associated with CHI3L1 genotypic frequencies." (PMID 37902124, 2023). "Odds ratios (ORs) and 95% confidence intervals (CIs) of the clinical status and CHI3L1 rs880633 and rs10399805 genotypic frequencies in 701 patients with prostate cancer." (PMID 37902124, 2023). "Odds ratios (ORs) and 95% confidence intervals (CIs) of the clinical status and CHI3L1 rs4950928 and rs6691378 genotypic frequencies in 701 patients with prostate cancer." (PMID 37902124, 2023). "Odds ratios (ORs) and 95% confidence intervals (CIs) of the clinical status and CHI3L1 rs6691378 genotypic frequencies in 405 prostate cancer patients aged >65 years." (PMID 37902124, 2023). "Odds ratios (ORs) and 95% confidence intervals (CIs) of the clinical status and CHI3L1 rs10399805 genotypic frequencies in 405 prostate cancer patients aged >65 years." (PMID 37902124, 2023). "LncRNA KCNQ1OT1 was also proved to promote cell progression of prostate cancer through targeting on miR-211-5p/CHI3L1 axis." (PMID 36471281, 2022). "KCNQ1OT1 expression was positively associated with Chitinase 3 Like 1 (CHI3L1) expression and significantly promotes prostate cancer (PCa) cell proliferation, invasion, and metastasis." (PMID 34827600, 2021). "Chitinase 3-like 1 (CHI3L1 or YKL40) is a secreted glycoprotein highly expressed in tumours from patients with advanced stage cancers, including prostate cancer (PCa)." (PMID 24981110, 2014). "Our team previously concluded that DAU inhibits macrophage M2 polarization through regulation of the PI3K/AKT signaling pathway and release of CHI3L1 from M2 macrophages, thus mitigating the malignant development of prostate cancer cells induced by M2 macrophages." (PMID 41438182, 2025). "Elevated CHI3L1(YKL40) expression has been observed in several cancer types, including brain, breast, lung, ovarian, colorectal, and prostate cancers." (PMID 38543093, 2024). "Chitinase 3‐like 1 (CHI3L1 or YKL40) is a secreted glycoprotein highly expressed in advanced stages of several cancer types, including prostate cancer (PCa)." (PMID 37902124, 2023).
autoimmune disease (17 papers, 2011 to 2024). A disorder resulting from loss of function or tissue destruction of an organ or multiple organs, arising from humoral or cellular immune responses of the individual to their own tissue constituents. "Furthermore, CHI3L1 is produced by a variety of inflammatory cells, including neutrophils, monocytes/macrophages, and osteoclasts, and its induction has been reported in patients suffering from many diseases, including several autoimmune disorders." (PMID 31717649, 2019).
hepatocellular carcinoma (17 papers, 2012 to 2025). A malignant tumor that arises from hepatocytes. "For instance, the rs880633 polymorphism within the CHI3L1 gene was identified as being correlated with the risk, progression and OS rate of patients afflicted with hepatocellular carcinoma (HCC)." (PMID 37902124, 2023). "Consistent with our results, CHI3L1 has been reported to be associated with poor prognosis in hepatocellular carcinoma." (PMID 36092895, 2022). "A study on the function of exosomal protein CHI3L1 in hepatocellular carcinoma demonstrated that CHI3L1 activated the TGF-β signaling pathway and promoted tumor progression by affecting gene expression." (PMID 33854614, 2021). "Here, considering that CHI3L1 is a liver specific/enriched protein, we use hepatocellular carcinoma as a model to study the function of CHI3L1." (PMID 30301907, 2018). "Based on this mechanism, targeting CHI3L1 may be a potential therapeutic strategy to inhibit hepatocellular carcinoma growth and metastasis." (PMID 40260255, 2025). "TGF-β signaling activation polarizes macrophages toward a M2-like phenotype by up-regulating SNAIL, and it has been reported that CHI3L1 could activate TGFβ signaling pathway in hepatocellular carcinoma." (PMID 34612767, 2021). "The latest study revealed that the protein level of CHI3L1 was elevated in serum and predicted the OS of HCC (hepatocellular carcinoma)." (PMID 40084401, 2025). "In liver cancer models using carbon tetrachloride (CCl4) and diethyl-nitrosamine (DEN), CHI3L1 facilitates the progression from chronic injury to fibrosis and hepatocellular carcinoma (HCC)." (PMID 40643503, 2025). "Furthermore, CHI3L1 is secreted by various cells, including hepatocytes, hepatic stellate cells, macrophages, and mesenchymal stem cells, to regulate hepatic injury, fibrosis, steatosis, and hepatocellular carcinoma through different signaling pathways." (PMID 40821115, 2025). "The overexpression of CHI3L1 was shown to increase tumor growth, whereas CHI3L1 knockdown inhibited the growth and invasion capacity of hepatocellular carcinoma (HCC) tumors in mice." (PMID 38177294, 2024). "In hepatocellular carcinoma (HCC), serum CHI3L1 does not appear to be a reliable diagnostic marker, as it cannot effectively distinguish HCC from liver cirrhosis." (PMID 40643503, 2025). "The text-mining scores of CHI3L1, EGFR, and VEGF in hepatocellular carcinoma were 0.780, 0.393, and 0.785, respectively, indicating a higher association of CHI3L1 and VEGF in the disease than for EGFR." (PMID 38177294, 2024).
tauopathies (17 papers, 2017 to 2023). "In the brain, CHI3L1 is expressed mainly by astrocytes and it increases in regions of neuroinflammation in AD and tauopathies, and also in other neuroinflammatory conditions." (PMID 33584248, 2020).